CLU (clusterin)
Diseases named in the same sentence as CLU in open-access papers (continued):
Sharing a sentence is not in itself a finding about the gene and the disease.
infection (31 papers, 2005 to 2025). The state of being infected such as from the introduction of a foreign agent such as serum, vaccine, antigenic substance or organism. "The results obtained from approaches (i) to (iv) indicate the relevance of the availability of secreted clusterin for successful Ctr infection." (PMID 39931630, 2024). "OC43 infection results in the recruitment of two C’ inhibitors, vitronectin (VN) and clusterin (CLU), from serum to the cell surface in an antibody-dependent mechanism." (PMID 35062233, 2021). "Humoral immune response related GO terms such as humoral immune response was common to both, while B cell mediated immunity (C1QB, HLA-DRA, C1QC, FCERIG, CIQA, CLU) was uniquely in subclinical infection." (PMID 32012176, 2020). "In this case, the clusterin, that is positive acute phase proteins, has seen great significance expressed in the first 10 days of infection." (PMID 32257894, 2019). "And then we used lentiviral infection to introduce a CLU cDNA expression vector into HepG2 cells to further confirm the role of CLU." (PMID 23457489, 2013). "Thus, future experiments will have to clarify how soluble recombinant PmpD mechanistically affects the CLU-dependent Ctr infection." (PMID 39931630, 2024). "In this study it is found that, serum amyloid A, haptoglobulin, hemopexin, α-macroglobulin and clusterin have been identified as major acute phase proteins and was found to quickly peaked in the first 10-day period after infection Toxoplasma gondii infection induced in mice." (PMID 32257894, 2019). "Clusterin, is an acute phase protein, which could agree that the stage of the infection and the process of interpretation." (PMID 32257894, 2019). "These increases were abrogated strongly by Ad-clusterin infection." (PMID 25148511, 2014). "Since the production of collagens, elastin and clusterin play an essential role in fibrotic responses after tissue injury, these results indicate that sub-lethal infection with CoV2 induces a chronic inflammatory response and may mediate fibrosis in the lungs of K18 mice at 21 DPI." (PMID 38092883, 2023). "Other upstream regulators such as CLU, KLF5, SP1 and TCF7L2 that were inhibited by ΔhtrA mutant infection have also been previously shown to be involved in apoptosis regulation." (PMID 37193047, 2022). "During infection with the ΔhtrA mutant, CBX5 was activated and CLU, KLF5, SP1, TCF7L2 and UBE2I were inhibited." (PMID 37193047, 2022). "For example, spermatozoa and Semen Derived Enhancer of Virus Infection (SEVI, small aggregates or fibrils) can bind HIV-1 and promote infection of target cells, whilst semenogelin-I inhibits direct infection of target cells and MUC6 and clusterin interfere with DC-SIGN mediated trans-infection." (PMID 25793526, 2015).
kidney disease (14 papers, 2014 to 2025). "More importantly, loss of Clusterin causes renal lipid accumulation and lipid metabolism-associated kidney disease, raising the possibility that Clusterin might regulate DM-induced testicular damage by modulating ferroptosis." (PMID 38992588, 2024). "It appears that methylation patterns in individuals with rapidly progressing kidney disease may be associated with higher expression of CLU since greater CLU expression correlates with loss of kidney." (PMID 35806113, 2022). "Clusterin, a glycoprotein encoded by the CLU gene, is expressed in many tissues, including the kidney, and clusterin expression is upregulated in the glomeruli of patients with various forms of kidney disease." (PMID 32913257, 2020). "Several experimental studies support the notion that clusterin has protective properties in various kidney diseases." (PMID 32913257, 2020). "Clusterin has been implicated in tubular protection and recovery in kidney injury models, while reduced urinary EGF is linked to impaired renal injury repair and worsened kidney disease outcomes." (PMID 40244015, 2025). "KIM-1 and clusterin estimation is a predictor biomarker for early-staged kidney diseases." (PMID 36418822, 2023). "Also, KIM-1 and clusterin estimation can be used as a predictor biomarker for early-staged kidney diseases." (PMID 36418822, 2023). "Clusterin is a protein whose concentration also increases in kidney disease." (PMID 35669103, 2022). "Potentially, urine cystatin B and clusterin may be used to diagnose active kidney disease allowing for more appropriate therapeutic interventions and ultimately better supportive care." (PMID 34324590, 2021). "Experimental studies also support the notion that clusterin may play a protective role in various forms of kidney disease." (PMID 32913257, 2020). "This study raises the possibility that clusterin could be used as a therapeutic target for Ang II-induced renal diseases." (PMID 25148511, 2014). "Taken together, our results indicate that glomerular clusterin is upregulated in DN, and this increase in clusterin expression may protect against oxidative stress-induced apoptosis in podocytes, providing a possible new therapeutic target for DN and other kidney diseases." (PMID 32913257, 2020).
neurological disease (14 papers, 2010 to 2025). "In consideration of its cellular, immunologic, and metabolic effects, clusterin has associations to various systemic inflammatory, metabolic, and neurological disorders; and their clinical outcome and phenotype, respectively." (PMID 36553017, 2022). "The role of ApoJ in AD was further supported by a GWAS (genome-wide association study) that identified the CLU locus as a risk factor for developing this neurological disease." (PMID 31077261, 2019). "A subset of genes was differentially expressed in the frontal cortex of RTT brains, some of which are known to be associated with neurological disorders (clusterin and cytochrome c oxidase subunit 1) or are involved in synaptic vesicle cycling (dynamin 1)." (PMID 20420693, 2010). "A focused examination of six AD-related genes – APOE, APP, BIN1, CLU, MAPT and PSEN1 – and SMARCA5, which has been linked to neurological disorders, revealed different expression patterns across cell types and AD." (PMID 41255979, 2025). "This connection with neurological disease progression was shared with another identified upregulated protein, CLU, a secreted glycoprotein involved in interaction with tau and α-synuclein." (PMID 37949225, 2023). "Based on functional similarities between clusterin and ApoE, the association between ApoE isoforms and WD onset, and the role of clusterin in copper-ATPase degradation, these molecules potentially could play a role in modifying the expression of neurological disease such as AD, MD, and WD." (PMID 23986700, 2013). "CLU and CO1 were of interest because of known associations with neurological disorders, and CO1 because of the described mitochondrial abnormalities observed in RTT." (PMID 20420693, 2010). "Previous comparative transcriptomics of the visual cortex have revealed that S100B and clusterin (apolipoprotein J), two stress proteins that are involved in neurological disorders characterized by hypoxic conditions, have a remarkably high expression in hooded seals compared to ferrets." (PMID 36243678, 2022).
cardiovascular disease (13 papers, 2013 to 2025). "Clusterin, or apolipoprotein J (ApoJ), is a glycoprotein associated with protein folding and linked to AD, metabolic disorders, and cardiovascular diseases." (PMID 40771197, 2025). "Clusterin (also named apolipoprotein J) has been associated with inflammation and lipid metabolism, as well as the pathophysiologic sequelae of these conditions, such as cardiovascular disease and malignancy." (PMID 23956692, 2013). "Furthermore given the high prevalence of cardiovascular diseases in the population examined and the association of Clusterin with these pathologies we evaluated Clusterin concentration variation in two groups with or without cardiovascular diseases." (PMID 26076476, 2015). "Nonetheless, a consensus is emerging based on studies of diverse disease states including neurodegeneration, cardiovascular disease and oncology that link secreted clusterin with cytoprotection or anti-apoptosis while intracellular forms mediate apoptosis." (PMID 30872998, 2019). "In presence of cardiovascular disease, Clusterin is significantly related to the most atherogenic components of lipid profile (total cholesterol and LDL), especially in women, suggesting its potential role in modulating cardiovascular metabolic risk factors." (PMID 26076476, 2015). "Herein, we summarize the known and potential roles of circulating and adipocyte-specific clusterin in cardiometabolism and discuss potential further investigations to determine if clusterin is a viable target to attenuate both metabolic and cardiovascular disease." (PMID 33717095, 2021). "The clusterin protein is of particular interest as a potential biomarker of MPS I cardiovascular disease because it is involved in morphologic transformation of vascular smooth muscle cells and present in human atherosclerotic plaques, but not in healthy normal aortas." (PMID 27064989, 2016). "We believe that clusterin may have utility as an in vivo biomarker of MPS I cardiovascular disease for several reasons." (PMID 26986213, 2016). "It is suggested that clusterin may be therapeutically exploited in MSC based therapy for cardiovascular diseases." (PMID 26962868, 2016). "The results of this study suggest that clusterin may be therapeutically exploited in stem cell based therapy for cardiovascular disease." (PMID 26962868, 2016). "CLU in its secreted form is a component of HDL-C and has role in metabolic and cardiovascular diseases." (PMID 40473938, 2025). "Further studies are required to determine if circulating clusterin levels are indeed elevated in human MPS I patients, and if those levels correlate with severity of their cardiovascular disease." (PMID 26986213, 2016). "Clusterin represents a promising biomarker to monitor efficacy of these therapeutic candidates in both preclinical and clinical studies for MPS I cardiovascular disease." (PMID 26986213, 2016). "Correlation between Clusterin and Lipid parameters in the two groups with or without cardiovascular diseases and divided by gender." (PMID 26076476, 2015). "Clusterin and lipid parameters concentrations by presence or absence of cardiovascular diseases and Kruskal Wallis test for comparisons between the two groups." (PMID 26076476, 2015).
metabolic disease (12 papers, 2017 to 2025). A congenital disorder (due to inherited enzyme abnormality) or acquired (due to failure of a metabolically important organ) disorder resulting from an abnormal metabolic process. "In particular, many studies have shown that clusterin is associated with various metabolic diseases." (PMID 33060605, 2020). "There are numerous identified mechanisms by which circulating clusterin could impact the risk of metabolic disease." (PMID 33717095, 2021). "For example, CLU can participate in the occurrence and development of neurological, fibrotic, and metabolic diseases by regulating cell endocytosis, apoptosis, and other processes." (PMID 39991767, 2025). "In summary, clusterin plays a protective role in a variety of metabolic diseases, but relatively little is known about the protective mechanisms of clusterin in these diseases, necessitating further investigation." (PMID 33060605, 2020). "This may be due to the young age and the absence of metabolic disorders in the participating children and adolescents, but additional studies are needed so that the role of clusterin in pediatric obesity can be clarified." (PMID 38396489, 2024).
kidney (6 papers, 2014 to 2023). "The upregulated genes included known acute kidney injury markers such as Havcr1 (Kim1), S100a6, Clusterin, Cdkn1a, and Spp127–29." (PMID 37898693, 2023).
inflammation (4 papers, 2022 to 2023). Aberrant reaction of the microcirculation characterized by movement of fluid and leukocytes from the blood into extravascular tissues. "Intravenously injected clusterin bound to the brain vascular endothelial cells and reduced the expression of neuroinflammatory genes in acute brain inflammation and AD models." (PMID 37511841, 2023).
adenocarcinoma (3 papers, 2012 to 2017). A common cancer characterized by the presence of malignant glandular cells. "Gastrin induces expression of clusterin in adenocarcinoma cells." (PMID 28902909, 2017). "We however also observed one protein that was down-regulated in SCC while up-regulated in adenocarcinoma (VWA8) and vice versa 7 proteins showing the opposite behavior (FAK2, PMM2, K2C5, SMCA5, FAD1, DTX3L and CLU)." (PMID 26930711, 2016).
immune diseases (1 paper, 2019). "Based on a review of related literature, CFH and clusterin might be related to immune diseases, and thus they were chosen for further verification." (PMID 31708932, 2019).
CLU also shares sentences with these, for which no sentence is quoted: acute myocardial infarction (6 papers); invasive breast carcinoma (4); steatosis (4); acute myeloid leukemia (3); biliary atresia (3); brain tumor (3); inflammatory myopathy (3); lipid metabolism disorders (3); Senile plaques (3); autism spectrum disorder (2); bacterial infection (2); Cerebral ischemia (2); cerebral microbleeds (2); chronic obstructive pulmonary disease (2); Glucose intolerance (2); Hepatic steatosis (2); lymphoid neoplasm (2); metastatic colorectal cancer (2); multiple system atrophy (2); ovarian serous cystadenocarcinoma (2); pancreatic (2); Parkinson (2); reproductive system disease (2); thymoma (2); acute lung injury (1); acute-on-chronic liver failure (1); aging (1); alcoholic cirrhosis (1); Apathy (1); arterial disease (1).
A further 102 diseases each share a sentence with CLU in 1 paper.